MET (MET proto-oncogene, receptor tyrosine kinase)
Diseases named in the same sentence as MET in open-access papers (continued):
Sharing a sentence is not in itself a finding about the gene and the disease.
melanoma (continued). "In a study by Pierce and others demonstrating increased anoikis resistance in melanoma cells following overexpression of the BRN2 transcription factor, a significant increase in c-MET expression and phosphorylation were observed." (PMID 37181747, 2023). "CAR-T/NK cell therapy for melanoma is developing rapidly, and clinical experiments using CAR-T cells are currently investigating c-MET, CD70, GD2, and VEGFR2 as melanoma-specific antigens." (PMID 38057843, 2023). "Four melanoma cell lines were treated with INF-γ, to induce the expression of PD-L1, and increasing concentrations of the MET-inhibitor Crizotinib were added, from 250 nM up to 1 μM." (PMID 37444518, 2023). "Cells representing two commercially available mucosal melanoma cell lines (GAK and HMVII) and one cell line obtained from a patient's vaginal melanoma were treated with MET or EGFR inhibitors, or combinations of these agents." (PMID 37679999, 2023). "First, we showed that JI130 and MEL56 inhibit cell migration in two invasive melanoma cell lines (MM029 and MM165) and downregulate the mRNA expression of the main EMT/invasion markers such as AXL, EGFR, MET, ZEB1, WNT5A, TGFβ, SNAI1, TWIST and MMPs." (PMID 37508519, 2023). "This pattern was also seen in a few (38%) primary melanoma cases, however, the correlation between the expression scores of MACC1 and MET is stronger in the metastatic melanomas than in primary melanomas." (PMID 37496665, 2023). "In contrast to anti-PD-1 therapy, which blocks T-cell inhibition and reactivates T-cells, MET inhibitors act by inhibiting IFN-γ-induced JAK–STAT signaling and its downstream PD-L1 expression in human melanoma cells." (PMID 37444518, 2023). "Given the mechanistic interaction between MACC1 and MET, it is logical to postulate roles of MACC1 in melanoma progression and metastasis." (PMID 37496665, 2023). "Another potential explanation is that activation of alternative signaling pathways may, in part, explain these results; indeed, the melanoma cell line that lacked an apparent response to MET inhibition, SK-MEL-28, has, for example, an EGFR mutation that may have contributed to this phenomenon." (PMID 37444518, 2023). "This review discusses several combination therapies that target melanoma biomarkers, such as BRAF, MEK, RAS, c-KIT, VEGFR, c-MET and PI3K." (PMID 35954441, 2022). "It has been shown that the low oxygen concentration decreases the sensitivity of melanoma cells to vemurafenib several times, which is probably due to the increased activation of the PI3K/AKT and HGF/c-MET pathways." (PMID 35565444, 2022). "Collectively, our study revealed that structural hybridization strategies yielded novel and potential c-MET/EGFR/PI3K/mTOR multi-target compounds, NSC777205 and NSC777205, with promising prospects for treating melanoma, renal, CNS, colon, and NSCLC cell lines." (PMID 34512327, 2021). "Overexpression of another tyrosine kinase receptor c-MET and its ligand HGF (hepatocyte growth factor) correlates with melanoma progression." (PMID 34203771, 2021). "c-MET/EGFR/PI3K/mTOR are therapeutic targets for NSC777205 and NSC777207 with consequent selective cytotoxic preferences for melanoma, renal, CNS, colon, and NSCLC cell lines." (PMID 34512327, 2021). "Receptor tyrosine kinases from the MET and ERBB family have been reported to be involved in melanoma progression and metastasis, as well as in the development of therapy resistance." (PMID 34063141, 2021). "In this article, various melanoma biomarkers including BRAF, MEK, RAS, c-KIT, VEGFR, c-MET and PI3K are described, and their potential mechanisms for drug resistance are discussed." (PMID 33807778, 2021). "MITF also regulates some genes that are important for melanoma survival (e.g., BCL2), proliferation (e.g., CDK2) and metastatic potential (e.g., c-MET)." (PMID 33746605, 2021).
melanoma (continued). "This combination (foretinib “MET inhibitor”and lapatinib or gefitinib) showed synergistic effect in different melanoma cells with different levels of RTK (cells express EGFR and MET)." (PMID 33918490, 2021). "In melanoma, foretinib inhibited HGF-induced cell migration and invasion, MET phosphorylation, tumor growth and lung metastases of B16F10 model." (PMID 33918490, 2021). "CAF-derived HGF activates the receptor MET and its downstream pathways MAPK and PI3K/AKT signalling in melanoma cells and leads to immediate resistance to RAF inhibition." (PMID 34067929, 2021). "At the transcriptional level, MITF controls genes involved in cell survival (BCL2, HIF1A, BCL2A1), migration (DIAPH1, MET) and proliferation (CDK2, TBX2, CDKN1B), providing important signals for growth of melanoma cells." (PMID 34289891, 2021). "NRAS, KIT, EGFR, MET, RAB27A, and other pro-progression proteins have all been found within exosomes released by melanomas." (PMID 35008286, 2021). "Upregulation of MET expression on tumor cells leads to an exacerbated HGF signaling and allows HGF to protect melanoma cells from apoptosis, highlighting a feed forward loop between HGF and cMET to favor treatment resistance." (PMID 33276788, 2020). "c-MET positive CD8 positive lymphocytes have been identified in human tumors; biopsy samples from four melanoma patients showed 8–35% of CD8 positive T-lymphocytes in close proximity to melanoma cells expressed c-MET." (PMID 32117721, 2020). "To summarize, this study is the first to demonstrate that curcumol, via the c-MET/PI3K/AKT and ERK/NF-κB signaling pathways, deceases melanoma cell proliferation and migration." (PMID 32194780, 2020). "Taken together, our findings suggested that curcumol attenuated melanoma progression and concomitantly suppressed ERK/NF-κB signaling and promoted miR-152-3p expression to inactivate the c-MET/PI3K/AKT signaling pathway." (PMID 32194780, 2020). "The decrease in c-MET, P13K and p-AKT protein expression following curcumol treatment in mouse melanoma B16 cells was notably attenuated by the miR-152-3p inhibitor." (PMID 32194780, 2020). "Circulating T-EVs from patients with stage IV melanoma carry a protein signature composed of the melanoma-specific protein tyrosinase-related protein-2 (TYRP2), very late antigen 4 (VLA-4), HSP70, and MET oncoprotein." (PMID 33081785, 2020). "In a murine model of melanoma, the inhibition of the receptor tyrosine kinase c-MET (HGF-R, hepatocyte growth factor receptor) reduces neutrophil recruitment in the tumor microenvironment and in the draining lymph nodes in response to immunotherapy." (PMID 32580431, 2020). "For this reason, we analysed direct involvement of these receptors in the invasion of melanoma cells inducing EGFR and MET up‐ and down‐regulations in examined cells." (PMID 31638339, 2019). "In particular, two were already described to be highly expressed in melanomas and involved in the regulation of cell invasion: PTGS2, also known as COX2, and MET oncogene." (PMID 30651148, 2019). "Here, we focused on the influence of simultaneous treatment of melanoma cells with selected inhibitors of EGFR - gefitinib or lapatinib, and MET - foretinib." (PMID 31649529, 2019). "MET expression together with dopachrome tautomerase (TYRP2), which is part of the melanin synthesis process, is part of a melanoma signature and prognostic for tumor progression." (PMID 30823658, 2019). "Foretinib (F, MET inhibitor) and lapatinib (L, EGFR inhibitor) used simultaneously were able to synergistically decrease the viability of melanoma cells, and also significantly diminish the invasive abilities and proteolytic activity of these cells." (PMID 31877948, 2019). "For instance, in melanoma patients, increased secretion of HGF from surrounding stromal cells increases MET pathway signaling in melanoma cells, resulting in resilience against BRAF targeted inhibitors." (PMID 31815659, 2019).
melanoma (continued). "This work for the first time shows that invasive abilities of melanoma cells are decreased after application of pairs of EGFR and MET inhibitors." (PMID 31649529, 2019). "Treating the melanoma cells with combination of BRAF inhibitor Vemurafenib and c-MET inhibitor AMG 337 or siRNA exhibited therapeutic benefits in BRAF mutant malignant melanoma." (PMID 31370278, 2019). "Epidermal and hepatocyte growth factors can stimulate invasive abilities of melanoma cells, while treatment with combination of their receptors' (EGFR and MET, respectively) inhibitors reduces viability of these cells, as we have previously shown." (PMID 31638339, 2019). "Our results indicate that both directed and spontaneous migrations (2D conditions) of melanoma cells are regulated by the EGFR and MET signalling." (PMID 31638339, 2019). "Melanoma is the most aggressive skin cancer and is responsible for 80% of the skin cancer-related death despite several targeted therapies, such as BRAF and MET inhibitors, have been developed." (PMID 29970086, 2018). "HGF can be bound by surface adhesion molecule CD44, which facilitates its presentation to c-MET, and HGF binding to c-MET upregulates the expression of the CD44v6 isoform in melanoma cells." (PMID 30513872, 2018). "The mechanisms behind the protective activity of HGF include upregulation of c-MET expression by MITF-M, a transcription factor of melanocytes and melanoma cells." (PMID 30513872, 2018). "Our research indicates the importance of personalized treatment of patients with melanoma since we have identified the EGFR and MET as potential therapeutic targets." (PMID 29719603, 2018). "In summary, these findings support the clinical evaluation of MET-directed targeted therapy to circumvent resistance to BRAF and MEK inhibitors in BRAFV600E mutant melanoma." (PMID 28147313, 2017). "miR-31 is also frequently silenced by DNA methylation in melanoma cells, and forced expression of miR-31 is reported to decrease cell migration and invasion, possibly through targeting SRC, MET, RAB27a, and MAP3K14." (PMID 28396701, 2017). "Using this method, we recently found that higher expression of HGF, MET, and VEGF-A genes correlates with lower sensitivity to a BRAF(V600E) inhibitor in melanoma cells." (PMID 28453553, 2017). "The positive correlation of HGF, MET, and VEGF-A expression and PLX4720 EC50 indicated that hypoxia-driven upregulation of these genes results in increased resistance to PLX4720 in melanoma." (PMID 28453553, 2017). "Only MET and GAB1 exhibited significant induction following vemurafenib or PD0325901treatment, indicating this induction may contribute to the underlying mechanism of HGF rescue and explain the unique ability of HGF to rescue BRAF mutant melanoma cells from MAPK pathway inhibition." (PMID 28147313, 2017). "In confirmation of that and other studies, we also found low levels of HGF and consistently high levels of MET and ERBB3 RNA in the four melanoma cell lines used in this study (Figure 5a1)." (PMID 28223541, 2017). "Downstream increases in ERK and AKT phosphorylation were also observed, suggesting that changes in total MET and GAB1 prime BRAF mutant melanoma cells for HGF-mediated rescue via downstream activation of the PI3K and MAPK signaling pathways." (PMID 28147313, 2017). "Specifically, hepatocyte growth factor (HGF), the cognate ligand for the RTK MET, has been shown to convey resistance to vemurafenib and a related analog, PLX4720, in BRAF mutant melanoma cell lines." (PMID 28147313, 2017). "In this study we observed a dominant role for the HGF/MET axis in mediating resistance to BRAF and MEK inhibitors in models of BRAFV600E and NRAS mutant melanoma." (PMID 28147313, 2017). "For example, EGFR, MET, and FGFR1 were highly expressed in 196 cell lines of carcinoma, melanoma, and glioma origin and high expression of EGFR correlated with decreased sensitivity to the MET inhibitor PHA665752." (PMID 27655711, 2016).
melanoma (continued). "MET pathway activation has been frequently reported as a mechanism of tumor recurrence in NSCLC (EGFRT790M) treated with erlotinib, in melanoma (BRAFV600E) treated with vemurafenib, and in GBM treated with bevazicumab." (PMID 26381735, 2015). "miR-31 has a known role in prostate cancer and melanoma, suppressing key cell cycle regulators and pro-oncogenic genes such as CDK1, E2F2, EXO1, FOXM1, MCM2, Src or MET." (PMID 25644061, 2015). "The activation of MET and SRC signaling was detected in two patient-derived melanoma cell lines with BRAFV600E that were resistant to BRAF inhibitor PLX4032." (PMID 24743024, 2014). "Etnyre and colleagues reported that c-MET and BRAF inhibitors hadsynergistic inhibitory effects when exposed in combination to melanoma cell lines." (PMID 25490933, 2014). "An important study demonstrated production of HGF by stromal cells in patients with melanoma, which resulted in activation of the HGF receptor MET, reactivation of the MAPK and PI3K pathways, and resistance to BRAF." (PMID 24743024, 2014). "We nominated SRC, MET, NIK and RAB27a as possible miR-31 targets in melanoma; these genes are known to play pro-tumorigenic roles in melanoma." (PMID 22948084, 2012). "miR-31 targets include oncogenic kinases such as SRC, MET, NIK (MAP3K14) and the melanoma specific oncogene RAB27a." (PMID 22948084, 2012). "Functional assays on a subset of these candidates, including MET, ASPM, AKAP9, IMP3, PRKCA, RPA3, and SCAP2, validated their pro-invasion activities in human melanoma cells." (PMID 20520718, 2010). "Among the 30 candidate metastasis genes is MET, a receptor tyrosine kinase (RTK) whose overexpression has been correlated with progression in multiple cancer types, including melanoma." (PMID 20520718, 2010). "Genes such as KRT14, GJA1, S100A7, S100A9, and EHF were higher in most melanomas while genes such as CITED-1, GDF15, QPRT, OCA2, c-MET and MME were more highly expressed in NHEM." (PMID 18442402, 2008). "Other identified genes, such as Cbp/p300-interacting transactivator (CITED-1), hepatocyte growth factor receptor (c-MET), and various homeobox genes have yet to be investigated in melanoma although some have been previously identified in metastatic melanoma." (PMID 18442402, 2008). "These include validated melanoma targets, such as CXCR4, MET and TYRP1." (PMID 40428399, 2025). "They developed an anti-METsynNotch→anti-MART1 TCR circuit, which selectively targeted MET+/MART1+ melanoma cells without affecting normal melanocytes." (PMID 40308611, 2025). "We investigated the distribution of MET expression and of Ecad (CDH1) and MITF, the transcriptional regulator of MET in melanocytes as well as marker of pigmented melanoma cells among primary tumors, extracranial metastases (TCGA-SKCM), and brain metastases (MBM_CHA)." (PMID 38386085, 2024). "Comparable with autocrine EGFR signalling discussed previously, autocrine c-MET/HGF signalling in disseminated cells and CTC clusters is hypothesised to contribute to the survival signalling necessary to evade anoikis during melanoma metastasis." (PMID 37181747, 2023). "Moreover, MET protein expression and MET phosphorylation after HGF stimulation were also documented in canine osteosarcoma and melanoma cell lines in that study, confirming activation of the receptor in vitro." (PMID 37104404, 2023). "Together, these findings demonstrate that the IFN-γ-induced PD-L1 expression in melanoma cells is negatively regulated by MET inhibition through the JAK/STAT3 signaling pathway and establish the colocalization and interaction between an RTK and a checkpoint protein in melanoma cells." (PMID 37444518, 2023). "The expressions of MACC1 and MET do not show significant differences based on patient age, gender, histologic subtypes of the primary melanoma, depth of invasion, and staging." (PMID 37496665, 2023).
melanoma (continued). "We have previously reported that the expression of MET and PD-L1 appear to positively correlate in metastatic melanomas, while this correlation is absent in primary melanoma and benign melanocytic nevi." (PMID 37444518, 2023). "Circulating sEVs of melanoma patients have a characteristic protein signature indicating metastasis, which is characterized by increased levels of tyrosinase-related protein 2 (TYRP2), very late antigen 4 (VLA4), HSP70 and the oncoprotein MET." (PMID 36167539, 2022). "In PTC and melanoma, the upregulation of MET and ERBB3 expression level induced by BRAFi conferred BRAFi resistance to BRAFV600E mutant carcinomas, and inhibitors of MET and ERBB family could reserve the resistance to BRAFi effectively." (PMID 33613767, 2021). "Within the “gene driver free” cohort, in addition to the ETV6→NTRK3 fusion positive LAC, we also detected three rearrangements in three independent melanoma patients: a rare EGFR ex26→LOC100996654 fusion, a BRAF intradomain duplication between ex10 and ex18 and a MET ex14 skipping." (PMID 34282766, 2021). "Particularly, a hyperactivation in EGFR and MET in cells with acquired resistance to BRAF inhibitors was shown; consequently, this combination (lapatinib+foretinib) was tested for its efficiency in BRAF resistant melanoma cells." (PMID 33918490, 2021). "In addition to NRAS mutations, several receptor tyrosine kinases (RTKs) such as c-KIT, EGFR, MET, and VEGFR have been reported to be involved in melanoma progression, invasion, or resistance to therapies, mainly targeting the MAPK pathway." (PMID 33918490, 2021). "Around 50% of the MITFBSs have been reported to locate in a 10 Kb segment around the transcription start sites (TSSs) in the melanoma cell line 501Mel, while more distant MITF bound enhancers, such as one −67 Kb away from the MET gene, have also been shown to be clinically relevant." (PMID 32605315, 2020). "Moreover, downstream effects of MET phosphorylation include activation of the MAPK signaling pathway, where more than 80% of melanomas harbors alterations." (PMID 32659961, 2020). "In addition, several lines of evidence point out a prominent role of the MET/HGF axis in tumor progression and resistance to therapy of several malignancies, including malignant melanoma." (PMID 32659961, 2020). "We hypothesized that curcumol suppresses the ERK/NF-κB signaling pathway and upregulates miR-152-p to suppress the c-MET/PI3K/AKT pathway and inhibit melanoma cell growth and invasion." (PMID 32194780, 2020). "Although a number of markers on EVs have been identified for a particular type of tumour (for example: EpCAM for ovarian cancer; VLA-4, TYRP2 and MET for melanoma; MIF for PDAC), so far, no universal markers have been found." (PMID 33081785, 2020). "In addition, western blot analysis further validated key changes at the protein level, with TWIST1, c-MET and β1-integrin levels dramatically increasing after induction of BRN2 expression in three of three melanoma cell lines." (PMID 32632141, 2020). "Dual luciferase reporter assays showed that a miR-152-3p mimic reduced the luciferase activity of pMIR-c-MET-WT but not that of pMIR-c-MET-MUT in mouse melanoma B16 cells." (PMID 32194780, 2020). "Activation of c-MET lncRNAs KCNQ1OT1, or downregulation of tumor suppressor microRNA MiR-22 by MALAT1 and miR-152–3p by HOTAIR was also found to increase metastatic growth of melanoma cells." (PMID 31370278, 2019). "This melanoma-specific “exosome signature” comprises of TYRP2 (tyrosinase-related protein-2), VLA-4 (very late antigen 4), HSP70 (heat shock protein 70), HSP90, and the MET onocoprotein." (PMID 30866509, 2019). "A new approach toward abrogating the HGF/c-MET signaling pathway using CAP and the SN could provide a novel strategy during the treatment of melanoma." (PMID 31126298, 2019).